GAS5 (growth arrest specific 5)
Diseases named in the same sentence as GAS5 in open-access papers (continued):
Sharing a sentence is not in itself a finding about the gene and the disease.
osteosarcoma (continued). "In osteosarcoma cells, dysregulated levels of GAS5 can impact cell growth and proliferation." (PMID 34386496, 2021). "However, the roles of GAS5 in bone diseases are still unclear, and most studies of GAS5 in bone diseases have been limited to studies of osteoporosis and osteosarcoma." (PMID 35155450, 2021). "In particular, miR-663a and ZBTB7A were found to protect osteosarcoma from endoplasmic reticulum stress-induced apoptosis, through the down-regulation of GAS5, while in a similar study the CtBP1-HDAC1/2-IRF1 transcriptional complex was also found to be down-regulated in osteosarcoma cells." (PMID 33076450, 2020). "Three miRNAs are related to GAS5 in osteosarcoma: miR-663a, mIR-203a and miR-221." (PMID 33076450, 2020). "GAS5 inhibited osteosarcoma cell growth and metastasis by targeting miR-203a." (PMID 32280304, 2020). "Furthermore, in one study, individuals with the genotype Del/Del of GAS5 rs145204276 had a smaller size of osteosarcoma tumor than those with Ins/Ins, and those with the genotype Del/Del rs145204276 had remarkably higher expression of GAS5." (PMID 32354045, 2020). "In addition, GAS5 also enhances the sensitivity of osteosarcoma cells to Cisplatin through the GAS5/miR-26b-5p/TP53INP1 axis, which may be a potential indicator for the treatment of osteosarcoma." (PMID 39015175, 2024). "Furthermore, over-expression of GAS5 enhanced DDP sensitivity of osteosarcoma cells." (PMID 37993867, 2023). "Up-regulation of GAS5 may be an effective therapeutic strategy for osteosarcoma." (PMID 37993867, 2023). "Hence, GAS5 enhanced the DDP sensitivity of osteosarcoma cells via miR-26b-5p." (PMID 37993867, 2023). "Here we aim to study the dysregulation of long non-coding RNA the growth arrest-specific transcript 5 (GAS5), and its roles in DDP-resistance of osteosarcoma." (PMID 37993867, 2023). "In this study, GAS5 was found to suppress cell proliferation and accelerate cell apoptosis of DDP-resistant osteosarcoma cells by regulating miR-26b-5p/TP53INP1 axis." (PMID 37993867, 2023). "Therefore, GAS5 may be a potential indicator for the management of osteosarcoma." (PMID 37993867, 2023). "Growth arrest specific 5 has been reported to affect the process of EMT, including in osteosarcomas." (PMID 34386496, 2021). "Downregulation of GAS5 in hFOB 1.19 and U2OS osteosarcoma cells enhanced their migration and invasion, along with an upregulated epithelial–mesenchymal transition (EMT), as evidenced by downregulated E-cadherin and upregulated vimentin, ZEB1, and ZEB2." (PMID 34386496, 2021). "Two different lncRNAs were down-regulated in osteosarcoma cells, the silence of TUSC7 promoted tumor growth in vivo, and the overexpression of GAS5 inhibited OS cell growth in vitro and in vivo." (PMID 29245999, 2017). "The GAS5-mediated inhibition of miR-221 also results in an increased expression of the aplasia ras homolog member I (ARHI), thereby preventing the EMT process in osteosarcoma cells." (PMID 39941145, 2025). "Although further studies are needed to determine whether Dio3os promotes osteosarcoma proliferation, existing studies indicate that lncRNAs, such as HAND2-AS1, lncRNA SARCC and lncRNA GAS5, are involved in the glycolytic process in osteosarcoma." (PMID 41235096, 2025). "In this study, GAS5 was down-regulated in DDP-resistant tissues and DDP-resistant osteosarcoma cells, suggesting that down-regulated GAS5 may be related to DDP-resistant of osteosarcoma." (PMID 37993867, 2023). "Furthermore, GAS5 over-expression improved DDP therapeutic effects on DDP-resistant osteosarcoma cells, demonstrating that GAS5 enhanced DDP-sensitivity of osteosarcoma in vitro." (PMID 37993867, 2023). "Similarly, it has been shown that WASIR2 knockdown suppressed the malignant activity of osteosarcoma cells; RPARP-AS1 and GAS5 can be used as prognostic biomarkers for lung adenocarcinoma (LUAD) and PCa, respectively." (PMID 36358967, 2022).
osteosarcoma (continued). "Therefore, upregulation of GAS5 and RHOB inhibited osteosarcoma cell proliferation, migration, and invasion in vitro, while overexpression of miR-663a induced malignancy in these cells." (PMID 34771549, 2021). "In our study, we did not study GAS5 levels in metastasis of osteosarcoma to other organs, and such studies should further help determine any specificity of GAS5-miR-21 in tissue specific metastasis." (PMID 34386496, 2021). "Our analysis revealed that compared to controls, GAS5 was significantly downregulated even in the osteosarcoma patients without metastasis (p < 0.05)." (PMID 34386496, 2021). "There are no reports concerning the role of GAS5 in osteosarcoma with respect to chemotherapy-related resistance." (PMID 33076450, 2020). "Furthermore, overexpression of GAS5 suppressed cellular proliferation, migration, and EMT in osteosarcoma cell lines." (PMID 29701689, 2018). "However, the chemotherapy-related resistance potentials of GAS5 in osteosarcoma has not been reported." (PMID 37993867, 2023). "However, GAS5 has not been evaluated for its potential role in metastasis of osteosarcomas, particularly the lung metastasis of osteosarcomas, which prompted us to first evaluate this lncRNA in patient samples and then explore the underlying mechanisms." (PMID 34386496, 2021).
liver cancer (25 papers, 2018 to 2026). An epithelial or non-epithelial malignant neoplasm that arises from the liver. "Moreover, down-regulation of GAS5 is associated with liver cancer progression, conferring a worse overall patient survival." (PMID 32549757, 2020). "Although GAS5 has been shown to promote EMT in liver cancer cells in vitro, further clinical data and in vivo experiments are needed to confirm their role in liver cancer metastasis." (PMID 41474641, 2026). "Expression analysis revealed that GAS5 is downregulated in NK cells isolated from liver cancer patients." (PMID 40781182, 2025). "al (2019) studied the role of the lncRNA GAS5 in regulating NK cell functions in liver cancer patients." (PMID 40781182, 2025). "qRT–PCR and western blot analyses of liver tissues confirmed a direct correlation between reduced Gas5 and Smarca4 expression and liver cancer prophylaxis." (PMID 40451925, 2025). "al (2019) showed that GAS5 overexpression promoted the killing effect of NK cells on liver cancer through regulating miR-544/RUNX3." (PMID 40781182, 2025). "Elevated expression of Gas5 lncRNA has been reported to occur in triple-negative breast cancer cells, polycystic ovary syndrome, osteoporosis, and liver cancer." (PMID 34575930, 2021). "Growth arrest-specific 5 (GAS5), highly up-regulated in liver cancer (HULC), miR-17-92a-1 cluster host gene (MIR17HG), and prostate cancer antigen 3 (PCA3) were the transcripts with the highest dysregulation score." (PMID 33593440, 2021). "In the context of liver cancer, GAS5 acts through a ceRNA mechanism, where it sponges miR-423-3p." (PMID 40451925, 2025). "In liver cancer, the role of GAS5 in carcinogenesis is particularly significant." (PMID 40451925, 2025). "In summary, GAS5 plays a multifaceted role in liver cancer carcinogenesis." (PMID 40451925, 2025). "It was reported that lncRNA GAS5 expression was significantly reduced in liver cancer and could be an independent prognostic factor for patients." (PMID 30069164, 2018). "Hence, downregulation of lncRNA GAS5 in the NK cells of liver cancer patients results in decreased natural cytotoxicity receptor NKp46 levels, a decline in INF-γ release and, eventually, in a reduction in NK cell cytotoxicity and CD107+ levels, thus facilitating tumor immune escape." (PMID 34943820, 2021). "This highlights the therapeutic potential of targeting the ceRNA network involving GAS5, miR-423-3p and SMARCA4 in liver cancer." (PMID 40451925, 2025). "Except for decreased SNHG2 (also named as GAS5) expression in liver cancer tissues, most of the SNHG family members were highly expressed in liver cancer tissues." (PMID 39237890, 2024). "In contrast to IL-2-activated NK cells, which show high expression of lncRNA GAS5 and intense IFN-γ release, lncRNA GAS5 is downregulated in liver cancer patient-derived NK cells, contributing to reduced NK-mediated cytotoxicity and tumor immune-escape." (PMID 34943820, 2021). "lncRNA GAS5 can inhibit tumor growth, and the overexpression of GAS5 can regulate miR-544/RUNX3 to enhance the killing effect of NK cells in liver cancer." (PMID 33274204, 2020). "Recently, more and more lncRNAs have been identified dysregulated in CC and regulating CC progression including XLOC_006390, highly upregulated in liver cancer (HULC), Growth arrest-specific transcript 5 (GAS5), Small nucleolar RNA host gene 20 (SNHG20), etc.." (PMID 32398968, 2020). "We next investigated whether inhibiting the oncogenic sponge effect involving GAS5, miR-423-3p and SMARCA4 could serve as a potential strategy for liver cancer intervention." (PMID 40451925, 2025). "Functional studies of GAS5 and its downstream targets in HCC were performed via small interfering RNA-mediated knockdown in various HCC cell lines, in vivo xenograft mouse models and spontaneous liver cancer models in Ras-transgenic mice." (PMID 40451925, 2025). "There are no reports on the role of GAS5 in chemosensitivity or chemoresistance in liver cancer." (PMID 33076450, 2020).
ischemic stroke (20 papers, 2019 to 2025). A stroke disorder caused by obstruction of blood flow to the brain, due to thrombotic (local blood clot formation) or embolic (due to a blood clot or other material traveling from another site) event. "Located on chromosome 1q25.1, the promoter region rs145204276 insertion-deletion variant of lncRNA GAS5 increases the risk of ischemic stroke in the Han population." (PMID 39766887, 2024). "Additionally, their findings underscore the potential therapeutic significance of GAS5 inhibition in mitigating neuronal apoptosis and ameliorating neurological deficits associated with ischemic stroke." (PMID 37705098, 2023). "Altogether, these observations suggest GAS5 promotes ischemic stroke injury through sponging miR-9 to derepress FOXO3." (PMID 39941145, 2025). "GAS5 is also involved in ischemic stroke progression by functioning as a competing endogenous RNA for miR-137, which regulates the Notch1 signaling pathway." (PMID 36439973, 2023). "The information in this paragraph strengthens the case for GAS5's role in both hypertension and ischemic stroke." (PMID 36439973, 2023). "Silencing of lncRNA GAS5 suppressed neuron apoptosis in ischemic stroke through inhibiting DNMT3B-dependent methylation of MAP4K4." (PMID 35451738, 2022). "Emerging evidence suggests that the long noncoding RNA (lncRNA) growth arrest special 5 (GAS5) plays crucial roles in the pathogenesis of ischemic stroke (IS)." (PMID 33937403, 2021). "LncRNA GAS5 promotes mouse ischemic stroke through acting as a competing endogenous RNA (ceRNA) for miRNA-137 to regulate Notch1 signaling." (PMID 33461167, 2021). "Previous studies indicate that miR-137 is one of miRNAs competitively bound by lncRNA GAS5 15, which is involved in neuronal apoptosis resulting from ischemic stroke." (PMID 33746585, 2021). "Consistently, in this study, we also found that the expression of lncRNA GAS5 and miR-137 was inversely correlated in ischemic stroke models." (PMID 33746585, 2021). "The expression of miR-137 is down-regulated in the MCAO-injured brain and in OGD-stimulated primary brain neurons and its upregulation can alleviate effects of growth arrest-specific 5 (GAS5) on the progression of ischemic stroke." (PMID 32496209, 2020). "Growth arrest-specific 5 (GAS5) is another candidate lncRNA for ischemic stroke pathology, due to its detrimental role in cell survival." (PMID 33321920, 2020). "Taken together, the present study demonstrated that STV-Na exerted neuroprotective effects by modulating microglia/macrophage polarization in ischemic stroke via the GAS5/miR-146a-5p sponge." (PMID 31434993, 2019). "LncRNA GAS5 might aggravate the progression of ischemic stroke through miR-137 mediated Notch1 signaling pathway." (PMID 35087519, 2021). "LncRNA GAS5 was observed to be upregulated in ischemic stroke." (PMID 33192490, 2020). "Additionally, high expression of lncRNA GAS5 in ischemic stroke patients was observed." (PMID 39766887, 2024). "Multiple studies reported differential expression of lncRNAs H19, GAS5, PVT1, TUG1, and MALAT1 in ischemic stroke." (PMID 39766887, 2024). "Moreover a study highlights that silencing GAS5 may inhibit neuronal apoptosis and improve neurological function in ischemic stroke, which contributes to better understanding of the pathologies of ischemic stroke and development of novel therapeutic options for this disease." (PMID 32624686, 2020).
glioblastoma (19 papers, 2011 to 2025). The most malignant astrocytic tumor (WHO grade IV). "HOTAIR and GAS5 levels were associated with 2-year overall survival and disease-free survival in patients with glioblastoma." (PMID 33053907, 2020). "Expression of GAS5 has been decreased in glioblastoma and its levels have been negatively correlated with miR-34a levels." (PMID 33634032, 2020). "Growth arrest specific 5 was downregulated by 2.9-fold (P-value 6.21 × 10−7) in a microarray of 22 glioblastoma multiforme compared with normal brain samples." (PMID 21407217, 2011). "Further, serum levels of GAS5 lncRNA were found to be linked with diminished tumor recurrence and progression, indicating the possible utilities of circulating HOTAIR and GAS5 in serving as potential reciprocal predictors of disease prognosis and survival in glioblastomas." (PMID 38366205, 2024). "Moreover, GAS5 overexpression inhibits cell viability, migration, and invasion in glioblastoma cells, along with impairing stemness and proliferation in GSCs." (PMID 39015773, 2024). "Interestingly, GAS5 has been related to the responsiveness of glioblastoma patients to TMZ, having potential therapy response prediction value." (PMID 31284524, 2019). "We found that GAS5 expression was downregulated in both LGG and glioblastoma multiforme (GBM) compared with normal brain tissue." (PMID 30853980, 2019). "Among them, the epigenetic regulators HOTAIR, GAS5, H19 and MALAT1 were found in serum and tumor samples from glioblastoma patients." (PMID 31284524, 2019). "Up-regulation of a number of oncogenic lncRNAs such as H19, MALAT1, SNHGs, MIAT, UCA, HIF1A-AS2 and XIST in addition to down-regulation of other tumor suppressor lncRNAs namely GAS5, RNCR3 and NBAT1 indicate the role of these lncRNAs in the pathogenesis of glioblastoma." (PMID 33634032, 2020).
lymph node metastasis (18 papers, 2015 to 2025). "Our previous research showed that carbonic anhydrate 9 (CA9) polymorphism is associated with a 4.5-fold increased risk of lymph node metastasis while growth arrest-specific 5 (GAS5) SNPs play a protective role in nodal invasion (OR 0.545, p = 0.043)." (PMID 34574033, 2021). "In conclusion, the rs145204276 polymorphic genotype of GAS5 can predict the risk of lymph node metastasis." (PMID 31673232, 2019). "Our overall results confirm a correlation between reduced GAS5 expression and poor clinical outcomes, and reveal an association with increased likelihood of lymph node metastasis (LNM) and distant metastasis (DM) in patients with early stage tumors." (PMID 29029523, 2017). "We collected all the relevant literatures about GAS5 expression levels associated with overall survival (OS), lymph node metastasis (LNM) and high tumor stage (II/III/IV) (HTS) from the PubMed and Web of Science." (PMID 29163187, 2017). "Our previous study proved that lncRNA growth arrest-specific 5 (GAS5) polymorphism could be a predictor for lymph node metastasis." (PMID 32878251, 2020). "In one previous study, GAS5 expression in CHOL was associated with advanced clinical stages and lymph node metastasis and showed potential in promoting proliferation and invasion by sponging miRNA mechanisms, particularly through the miR-1297 axis." (PMID 39958058, 2025). "A previous study showed that GAS5 downregulation is associated with higher TNM stages, lymph node metastases, poor overall survival, and increased resistance to chemotherapy." (PMID 39958058, 2025). "In patients with PTC, a lower level of GAS5 expression is linked with poor prognosis, tumour nodules metastasis (TNM) staging, multiple cancer foci, and lymph node metastasis." (PMID 39558949, 2024). "Growth-arrest-specific transcript 5 (GAS5) levels are negatively associated with tumor size, histological grade, and lymph node metastasis." (PMID 36613528, 2022). "Some lncRNAs, such as GAS5, rp11-190d6.2, and nbat-1 were downregulated in OV cells, and were significantly associated with histological grading, FIGO staging, and lymph node metastasis." (PMID 32950050, 2020). "Univariate analysis and COX analysis showed that lymph node metastasis, Gas5 expression, TNM staging, distant metastasis and tumor differentiation were closely related to the prognosis of CRC patients (P < 0.05)." (PMID 29308053, 2018). "We also performed a sensitivity analysis of lymph node metastasis and GAS5, and got similar results." (PMID 29163187, 2017). "It demonstrated that patients with low GAS5 expression in tumor tissues were more prone to lymph node metastasis." (PMID 29163187, 2017). "The results demonstrated that low expression levels of GAS5 predicted poor OS in various cancers and patients with low GAS5 expression in tumor tissues were more prone to lymph node metastasis." (PMID 29163187, 2017). "Based on the differential expression levels of GAS5, seven studies reported 443 patients with lymph node metastasis." (PMID 29163187, 2017). "In conclusion, although the GAS5 SNP rs145204276 did not affect the PCa susceptibility, our study indicated men with PCa and carrying GAS5 SNP rs145204276 are less likely to develop lymph node metastasis, especially in the age older than 65 years' group." (PMID 31673232, 2019). "To determine whether GAS5 rs145204276 can affect the progression of CRC, we also explored the associations between GAS5 rs145204276 and Lymph node metastasis and Distant metastasis of CRC." (PMID 27863421, 2016). "In addition, analysis in the preoperative and postoperative plasma samples showed the postoperative levels of circulating GAS5 and H19 significantly decreased, and circulating GAS5 levels in the patients with a positive lymph node metastasis state decreased after surgery." (PMID 31744046, 2019).
lymph node metastasis (continued). "The clinic pathological features of the patients, such as overall survival (OS), lymph node metastasis (LNM) and high tumor stage (II/III/IV) (HTS), are also highly correlated with the level of GAS5 expression in these cancers." (PMID 29163187, 2017).